PTPN1 (protein tyrosine phosphatase non-receptor type 1)
Diseases named in the same sentence as PTPN1 in open-access papers (continued):
Sharing a sentence is not in itself a finding about the gene and the disease.
Insulin resistance (continued). "The increase in Ptpn1 expression in the ARC and central insulin resistance could therefore be further examples of accelerated ageing in mice that have undergone IUGR followed by catch-up growth." (PMID 30043179, 2018). "Besides PTPN1 and STAT5A, some other genes like FASN, TAP1, which are also involved in insulin resistance, have close relationship with MCAT." (PMID 29088862, 2017). "Since PTPN1 and STAT5A were demonstrated to impair insulin signaling, MCAT and its network may be novel mechanisms as to the offspring insulin resistance affected by intrauterine hyperglycemia." (PMID 29088862, 2017).
type 2 diabetes (203 papers, 2006 to 2026). "Protein tyrosine phosphatase 1B (PTP1B), encoded by PTPN1, is a potential target for treatment of type-2 diabetes and Alzheimer's disease." (PMID 29093681, 2017). "PTP1B is encoded by the PTPN1 gene located on chromosome 20q13 showing linkage with type 2 diabetes (T2D) in several populations." (PMID 16677372, 2006). "Type 2 Diabetes case-control association study of the 14 PTPN1 SNPs." (PMID 16677372, 2006). "Of note, trials assessing the efficacy of several PTPN1 inhibitors for the treatment of type 2 diabetes were halted due to low efficacy and toxicities, including vomiting and diarrhoea." (PMID 38334623, 2024). "Eight of these lay between PTPN1 and CYP24A1, a region of interest subject to amplification in human cancer cell lines and associated with complex traits such as type 2 diabetes." (PMID 17705864, 2007). "Related studies indicate that linoleic acid is a multi-target inhibitor of PTPN1, PTPN9, and PTPN11, potentially exerting an anti-diabetic effect to prevent type 2 diabetes." (PMID 41554047, 2026). "Several PTPs, such as PTPN1, PTPN2, PTPN9, PTPN11, PTPRS, and DUSP9, disrupt insulin signaling and trigger type 2 diabetes, indicating that PTPs are promising drug targets for the treatment or prevention of type 2 diabetes." (PMID 35204821, 2022). "Diverse PTPs, such as PTPN1, PTPN2, PTPN9, PTPN11, PTPRS, and DUSP9, have been reported to attenuate insulin signaling and trigger type 2 diabetes, indicating that PTPs are promising drug targets for the treatment or prevention of type 2 diabetes." (PMID 35204821, 2022). "Some PTPs, such as PTPN1, PTPN2, PTPN9, PTPN11, PTPRS, and DUSP9, have been shown to attenuate insulin signaling and trigger type 2 diabetes, indicating that PTPs are promising drug targets for the treatment or prevention of type 2 diabetes." (PMID 35204821, 2022). "Recent advances in the generation of ptp inhibitors and positive outcomes in clinical trials of PTPN1 (protein tyrosine phosphatase, non-receptor type 1; formerly PTP1B) antisense for treatment of type 2 diabetes may soon lead to the use of ptps as markers and novel targets in oncology." (PMID 18317580, 2008).
breast cancer (100 papers, 2003 to 2025). A primary or metastatic malignant neoplasm involving the breast. "Previous studies have shown that PTPN1 is associated with a significantly improved OS in breast cancer patients." (PMID 37936713, 2023). "The gene encoding for PTP1B, PTPN1, is located on chromosome number 20q13, which is often augmented in breast cancers, and it is overexpressed in at least 70% of all breast cancers." (PMID 35159385, 2022). "Down-regulated genes in HER2-negative cell lines are directly linked to HER2 overexpression and HER2-positive breast cancers (e.g., Stat, Ptpn1, Pak1, Efnb1)." (PMID 34775465, 2021). "Over-expression of PTPN1 has been linked to colon cancer and breast cancer development and progression." (PMID 32226775, 2020). "Recently, our group and Dr. Benjamin Neel’s laboratory demonstrated that deletion of PTPN1 activity in mmtv-neu transgenic mice by breeding with PTPN1-deficient mice caused significant mammary tumour latency and resistance to lung metastasis." (PMID 18317580, 2008). "Finally, our results demonstrated that PTPN1 was associated with immune infiltration and immune checkpoint gene expression in breast cancer." (PMID 37936713, 2023). "Interestingly, PTPN1 is located within 20q13, a region frequently amplified in ovarian and breast cancers and usually associated with a poor prognosis." (PMID 18317580, 2008). "Previous studies have highlighted the roles of PRL2 and PTPN1 in promoting breast cancer metastasis through the activation of extracellular signal-regulated kinase 1/2 and the upregulation of the expression of vitamin D receptors, respectively." (PMID 40016288, 2025). "For example, PTPN1 plays a positive role in human epidermal growth factor receptor 2 (HER2) signalling during breast cancer development." (PMID 38334623, 2024). "Immunohistochemistry and immunoblotting were used to investigate the relationship between PTPN1 expression, immune cell infiltration, and immune checkpoint gene expression in human breast cancer tissues and a mouse xenograft model." (PMID 37936713, 2023). "The cell counting kit-8 (CCK-8) assay was performed to examine the effects of PTPN1 level on the sensitivity of breast cancer cells to paclitaxel." (PMID 37936713, 2023). "Specifically, lncRNA UCA1 accelerates the proliferation of breast cancer cells based on the miR-206/PTPN1 axis." (PMID 35957898, 2022). "PTPN1, which is required for invadopodia formation, promotes invasiveness of breast cancer cells by negatively regulating PTEN and facilitates human epidermal growth factor receptor 2 (HER2)-induced breast tumorigenesis with lung metastasis." (PMID 35957898, 2022). "PTPN1 is targeted by miR-542-5p and miR-34c in glioma, miR-146b and miR-338-3p in gastric cancer, and miR-193a-3p in breast cancer." (PMID 35957898, 2022). "In recent studies, the overexpression of PTPN1 was detected in several cancer types such as colon cancer and breast cancer." (PMID 32226775, 2020). "Moreover, the amplification of the PTPN1 gene was determined to be a marker of a severe course of the disease, determining worse prognosis in breast cancer, gastric cancer, and CRC." (PMID 39000142, 2024). "This could be ascribed to their interaction with various breast cancer-associated protein targets such as CAs, AKR1B1, ADORA3, PTPN1, ESR2, and EGFR." (PMID 39482666, 2024). "We found that PTPN1 expression is associated with the extent of immune infiltration of CD163+ M2-like TAMs and CD8+ T cells and the expression of the immune checkpoint protein, PD-L1, in breast cancer." (PMID 37936713, 2023). "Previous studies have also suggested that the PTPN1 protein level is dramatically increased in breast cancer tissues and that PTPN1 promotes the proliferation and suppresses the apoptosis of both ErbB2-positive and triple-negative breast cancer (TNBC) cell lines." (PMID 37936713, 2023).
breast cancer (continued). "To further validate the role of PTPN1 in the immune microenvironment of breast cancer in vivo, we knocked down the expression of PTPN1 in 4T1 breast cancer cells using two different short hairpin RNAs (shRNAs; shPTPN1#1 and shPTPN1#2), and a non-target shRNA as a control (shCtrl)." (PMID 37936713, 2023). "We found that PTPN1 knockdown inhibited breast cancer cell tumorigenesis in vivo." (PMID 37936713, 2023). "As with breast cancer, PTPN1 and PTPN11 also serve as oncogenic factors in lung cancer." (PMID 35957898, 2022). "This locus contains 24 protein-coding genes, among which at least 10 (e.g. NCOA3, SNAI1/Snail1, CEBPB and PTPN1) are involved in mammary gland development, ERα-related regulation, or breast cancer, suggesting an importance of this locus for mammary gland morphogenesis." (PMID 31642473, 2019). "Among the altered genes, ARHGAP26 and MLLT1 have been associated with leukemia-specific translocations, DDHD2, FGFR1 and PTPN1 have tumor-promoting potential in breast cancer, and CTNNA3 may promote tumor formation in urothelial cancer." (PMID 20428235, 2010). "The recent identification of PTPN1 as a potential oncogene in breast cancer may be key in focusing research efforts toward this relatively poorly known gene family." (PMID 18317580, 2008). "Hence, it was proposed that individuals with ErbB2-positive breast cancer might benefit from pharmacological inhibition of PTPN1 activity in combination with anti-ErbB2 therapies." (PMID 37936713, 2023). "Importantly, we further confirmed the abnormal expression of PTPN1 in breast cancer." (PMID 37936713, 2023). "Pharmacological inhibition of PTPN1 using a small molecule inhibitor MSI-1436 antagonises HER2 signalling and blocks the growth of breast cancer xenografts in mice." (PMID 38334623, 2024). "For instance, PTPN1 in hepatocellular carcinoma, PTPN11 in colon cancer and PTPN12 in breast cancer can be both tumor promoters and tumor suppressors based on different molecular pathways." (PMID 35957898, 2022). "PTPN family members have been extensively investigated in breast cancer, with PTPN1 and PTPN11 driving the progression of breast cancer." (PMID 35957898, 2022). "To validate the correlation of PTPN1 expression with immune cell infiltration, we analyzed the infiltration of TAMs and CD8+ T cells by performing IHC staining in serial sections of human breast cancer specimens from the same patient." (PMID 37936713, 2023). "PTPN1 expression showed a significant positive correlation with most types of immune cells, including B cells, CD4+ T cells, CD8+ T cells, neutrophils, macrophages, and dendritic cells in most cancer types, especially in breast cancer (P < 0.05 for all)." (PMID 37936713, 2023). "Although PTP1B (PTPN1) was previously known could dephosphorylate some receptor protein tyrosine kinases, studies showed that inhibition of PTP1B could be a new therapeutic strategy for breast cancer, including triple-negative breast cancer." (PMID 33246450, 2020). "PTPN5 is in the same non-receptor Cys-based classical PTPs as PTPN1 and PTPN11, which promoted tumorigenesis in ovarian cancer, gastric cancer, prostate cancer, breast cancer, leukaemia, colorectal cancer and uveal melanoma." (PMID 32928212, 2020).
metabolic diseases (39 papers, 2006 to 2026). "Thus, our data indicate that PTPN1 variants may modulate the lipid profile, thereby influencing susceptibility to metabolic disease." (PMID 16677372, 2006). "Thus, although still not studied in relation to successful aging, the observed interaction among genetic variants of IGF1R and PTPN1 in Danish long‐lived could reflect a conserved mechanism of cellular signalling, involved in the development of metabolic diseases and tumorigenesis." (PMID 29577582, 2018). "The non-receptor tyrosine phosphatase PTPN1 (also known as PTP1B) constitutes the paradigm of PTP enzymes and a suitable drug target for cancer and metabolic diseases, and PTPN1 protein expression has been shown to correlate with metastasis and poor prognosis in several human cancers." (PMID 31837707, 2019).
Hyperglycemia (36 papers, 2010 to 2025). An increased concentration of glucose in the blood. "miRNA-206s inhibitory effects were reversed in the livers upon reintroducing PTPN1, indicating that PTPN1 is involved in mediating the protective effects of miRNA-206 against hyperglycemia and hepatosteatosis." (PMID 38993840, 2024). "In conclusion, MCAT and its crosstalk with PTPN1, STAT5A are increased in the umbilical cord blood affected by maternal uterine hyperglycemia." (PMID 29088862, 2017). "MCAT and its network with PTPN1, STAT5A are regulated in umbilical cord blood affected by maternal intrauterine hyperglycemia." (PMID 29088862, 2017).
metabolic syndrome (34 papers, 2006 to 2025). A cluster of metabolic risk factors for CARDIOVASCULAR DISEASES and TYPE 2 DIABETES MELLITUS. "Taken together, our data indicate that PTPN1 variants may modify the lipid profile, thereby influencing susceptibility to the metabolic syndrome in the French population." (PMID 16677372, 2006). "Multiple consistent associations were observed between SNPs rs941798C/G and rs2426159A/G and metabolic parameters reflecting insulin sensitivity and the lipid profile, thereby suggesting that PTPN1 may influence susceptibility to the metabolic syndrome in a French population." (PMID 23762820, 2013). "Further genetic and functional studies of the contribution of PTPN1 variation to the metabolic syndrome and related traits are clearly warranted." (PMID 16677372, 2006). "However, our association analysis of metabolic syndrome quantitative traits supports the hypothesis of a possible influence of PTPN1 genetic variation on insulin sensitivity, plasma lipid levels and hypertension which are characteristics of the metabolic syndrome." (PMID 16677372, 2006).
colorectal cancer (25 papers, 2016 to 2026). A primary or metastatic malignant neoplasm that affects the colon or rectum. "To get a better understanding of the role of PTP1B in colorectal cancer, we first investigated expression levels of the gene encoding this phosphatase (PTPN1) using publicly available array data sources." (PMID 26942883, 2016). "Network analysis of the PTPN1 gene associations in colorectal cancer shows links with several oncogenes such as EGFR, STATs, and Src." (PMID 26942883, 2016). "Using cbioportal, we further analyzed the TCGA colorectal cancer dataset, revealing an alteration in the PTPN1 gene (e.g. amplification, mutation, upregulation) in 45.1% of cases and a trend towards worse survival for patients with alterations in the PTPN1 gene." (PMID 26942883, 2016). "Tumors with higher PTPN1 expressiontended to show elevated levels of both ER stress regulators, pointingto a possible transcriptional link between PTP1B and the unfoldedprotein response pathway in colorectal cancer." (PMID 41432362, 2026). "Colorectal cancer remains a major clinical challenge, and dual targeting of PTPN1 and PTPN2 represents a promising strategy to modulate conserved phosphatase signaling relevant to tumor biology and immune regulation." (PMID 42079868, 2026). "Among them, PTPN1 expression is related to poor prognosis in colorectal cancer patients through dephosphorylation of the Tyr530 site of Src, which activates the Src signaling pathway and enhances the oncogenicity of colon cancer." (PMID 35957898, 2022). "The TCGA Colorectal 2 dataset compares normal colon to 7 subtypes of colorectal cancer, and shows a PTPN1 copynumber increase for 6 of these cancer types." (PMID 26942883, 2016). "In colorectal cancer, PTPN1, PTPN2 and PTPN18 undoubtedly drive its progression." (PMID 35957898, 2022). "Christensen’s study concluded that miR-362-3p may be a novel prognostic marker for colorectal cancer, and this study hypothesizes that the positive effects of augmented miR-362-3p expression may in part be mediated through hypothetical target protein 1 (PTPN1)." (PMID 33526047, 2021). "Since we observed a significant upregulation of PTP1B protein and PTPN1 mRNA levels in colorectal cancer, the question rises how this upregulation occurs." (PMID 26942883, 2016). "In colorectal cancer, researchers found that miR-362 may be involved in the regulation of the tumor cell cycle by affecting the expression of E2F1, USF2, and PTPN1." (PMID 32582765, 2020). "CCLE analyses showed that in esophagus cancer cell lines, PTPN1, PTPN4 and PTPN12 were highly expressed; in gastric cancer cell lines, PTPN2 and PTPN12 were highly expressed; in colorectal cancer cell lines, PTPN12 was highly expressed while PTPN22 was downregulated." (PMID 32536826, 2020). "A critical finding was the specificand significant upregulation of PTPN1 in tumor-infiltratingB cells ( p = 0.030), a change not observed in Tor myeloid cells, highlighting a potential role for B cell-specificPTP1B signaling in the colorectal cancer microenvironment." (PMID 41432362, 2026).
colon carcinoma (21 papers, 2009 to 2024). "However, in our study, nearly 50% of colon tumors have a mutation in PTPN1." (PMID 27855221, 2016). "Several lines of evidence support our conclusions about the role of PTPN1/cortactin axis in the mechanism of curcumin-induced inhibition of colon cancer cell migration." (PMID 24465712, 2014). "In conclusion, we have shown that pTyr421-cortactin is overexpressed in colon cancer, that curcumin modulates the activity of PTPN1 phosphatase to decrease cortactin phosphorylation and interaction with CTNND1, and ultimately to decrease colon cancer cell migration." (PMID 24465712, 2014). "Similarly, the abnormal expression of PTPN1 in gastric cancer, ovarian cancer, colon cancer and other tumors can promote cell proliferation, colony formation and migration, while reduce the apoptosis of cancer cell lines, and the overexpression of PTPN1 is associated with poor prognosis." (PMID 38533261, 2024). "We next sought to determine whether curcumin activates PTPN1 colon cancer cells." (PMID 24465712, 2014). "Although the role of the PTPN1/cortactin axis has been identified in the mechanism of CUR-induced inhibition of colon cancer cell migration, additional studies are required to establish the mechanism by which CUR activates PTPN1." (PMID 29743988, 2018). "However, in the tested tumor samples, PTPN1 expression was not affected, thus raising a possibility that relative PTPN1 deficiency should not be a factor limiting the efficacy of curcumin or other drugs targeting PTPN1/cortactin in potentially reducing colon cancer cell migration and metastasis." (PMID 24465712, 2014). "Collectively, these data suggest that curcumin is an activator of PTPN1 and can reduce cell motility in colon cancer via dephosphorylation of pTyr421-CTTN which could be exploited for novel therapeutic approaches in colon cancer therapy based on tumor pTyr421-CTTN expression." (PMID 24465712, 2014). "Curcumin decreased the levels of pTyr421 cortactin in colon cancer cells in vitro by physically interacting with the non-receptor type 1 protein tyrosine phosphatase (PTPN1; PTP1b) to increase its activity, and dephosphorylate cortactin, thus reducing cancer cell migration." (PMID 24465712, 2014).
prostate carcinoma (20 papers, 2013 to 2025). A carcinoma that arises from epithelial cells of the prostate gland. "PTPN1 appeared as a good candidate since it has previously been implicated with the progression of prostate cancer along with evidence that the androgen receptor is a transcriptional regulator of PTPN1." (PMID 23372565, 2013). "PTP1B (also known as PTPN1) is a protein tyrosine phosphatase, whose expression is amplified by androgens in prostate cancer cells and which dephosphorylates IGFR, Jak2, and Tyk2, kinases crucial to cytokine signaling pathways." (PMID 31118931, 2019). "While PTPN1 and PTPN12 were implicated in prostate cancer biology, the involvement of PTPN2 in prostate cancer is not documented." (PMID 37509645, 2023). "PTPN1 and PTPN2 are highly related PTPs, but PTPN2 has not been implicated in prostate cancer." (PMID 37509645, 2023). "With regard to other GEMMs, PTP1B (PTPN1), an androgen-regulated phosphatase, acts as a HFD-dependent tumor suppressor in prostate cancer driven by the absence of Pten, such as in the Pten-/-Ptpn1-/- mice model." (PMID 31052319, 2019).